GRIN2B (glutamate ionotropic receptor NMDA type subunit 2B)
Diseases named in the same sentence as GRIN2B in open-access papers (continued):
Sharing a sentence is not in itself a finding about the gene and the disease.
schizophrenia (continued). "In our dataset, we detected AMPA and NMDA receptor subunits associated with schizophrenia (i.e., GRIA1 and GRIN2A) and with a spectrum of DD/ID, ASD and seizures, often in co-morbidity (GRIA3, GRIN1, GRIN2A, and GRIN2B)." (PMID 28713243, 2017). "Specific genetic risk factors seem to dispose patients with schizophrenia to develop OCS and risk-conferring polymorphisms has been defined in SLC1A1, BDNF, DLGAP3, and GRIN2B and in interactions between these individual genes." (PMID 26556409, 2014). "In patients with schizophrenia, a significant effect of GRIN2B (human NMDA receptor 2B subunit gene, NR2B) genotype on habituation suggests a bigger role for NR2B mediated processes." (PMID 25374541, 2014). "As a comparator, we also included a mouse mutant that carries a null mutation (C456Y) in Grin2b, a gene that is not genetically associated with schizophrenia, but is associated with autism spectrum disorder (ASD) and DD/ID." (PMID 41022686, 2025). "Likewise, given the key influence of NMDA receptor hypofunction in the pathophysiology of schizophrenia, the association GRIN2A and GRIN2B with presynaptic mGlu2 and mGlu3 in the context of schizophrenia certainly warrants further exploration." (PMID 38277461, 2024). "In 2011, a de novo GRIN2B pathogenic variant (c.2473T4G; p.L825V) was reported for the first time, and in the same paper, two additional de novo pathogenic GRIN2A variants were identified in two patients with sporadic schizophrenia." (PMID 39596051, 2024). "Although GRIN2B is not rated as a putative effector gene for schizophrenia, it has been shown that variants in this gene are associated with this condition in a Siberian and a Han Chinese population." (PMID 38383672, 2024). "We did not reveal any associations of GRIN2A and GRIN2B polymorphisms with leading (positive vs. negative) symptoms or type of course (continuous vs. episodic) of schizophrenia." (PMID 34685369, 2021). "It is quite conceivable that GRIN2A and GRIN2B, via this DDCS, modulate the activity of the ascending monoaminergic pathways and thus cause the ‘positive’ component of schizophrenia, while changes in the prefrontal cortex and hippocampus cause negative and cognitive components to arise." (PMID 34685369, 2021). "The genotypes and alleles frequency analysis of GRIN2A and GRIN2B polymorphisms detected no “modifier loci” regarding positive or negative leading symptoms of schizophrenia." (PMID 34685369, 2021). "This may indicate that dysfunction of NMDA receptor subunits can serve as a trigger for the development of schizophrenia, and significant mutations in the GRIN2A and GRIN2B genes can affect early or late onset." (PMID 34685369, 2021). "In this study, we did not identify associations of the GRIN2A and GRIN2B genes with leading symptoms or course types of schizophrenia." (PMID 34685369, 2021). "The significance of genetic variation of GRIN2A and GRIN2B fits well with the glutamate hypothesis for the pathophysiology of schizophrenia." (PMID 34685369, 2021). "In addition, the GRIN2A and GRIN2B genes, encoding the GluN2A (NR2A) and GluN2B (NR2B) subunit of the NMDAR respectively, are identified schizophrenia risk genes." (PMID 31824347, 2019). "However, most previous studies of SNP associations with schizophrenia only investigated one or two genes in NMDARs, particularly GRIN1, GRIN2A, and GRIN2B." (PMID 26819771, 2016). "Several investigations have presented strong evidence indicating that genetic variants in glutamate ionotropic receptor NMDA type subunit 2B (GRIN2B), which encodes the NR2B subunit of NMDA receptors, may modify susceptibility to schizophrenia in offspring of HSV-2-seropositive mothers." (PMID 40806558, 2025). "In summary, specific genetic risk factors predispose patients with schizophrenia to develop OCS induced by antipsychotic treatment, and risk-conferring polymorphisms in genes linked to the glutamatergic system, such as SLC1A1, DLGAP3, and GRIN2B, have been identified." (PMID 37627285, 2023).
schizophrenia (continued). "In this study, we examined the contribution of GRIN2A and GRIN2B polymorphisms to the clinical features of schizophrenia, specifically the leading symptoms (negative or positive), course type (continuous or episodic), as well as the age of onset of the disease." (PMID 34685369, 2021). "Since Grin2b encodes a critical subunit of N-methyl-D-aspartate receptor (NMDAR), an important glutamate receptor involved in learning/memory and a variety of neurological disorders including autism and schizophrenia, TBR1 regulates neuronal activity and functions by controlling Grin2b expression." (PMID 30792833, 2019). "In iPSC-derived neurons from patients with schizophrenia, researchers have identified changes in the expression of various glutamate receptor subunits, including GRIN2A, GRIN2B, GRIK1, GRIK2, and GRM1, GRM7, as well as glutamate transporter genes." (PMID 39596430, 2024). "In some analyses, GRIN1, GRIN2A and GRIN2B were unchanged, but GRIN2A vs. GRIN2B ratio decreased in the PFC of patients with schizophrenia." (PMID 36833173, 2023). "This study indicates the likely contribution of the GRIN2A, GRIN2B, GRM8, SLC1A2, and SLC17A7 genes to the development of clinical heterogeneity in schizophrenia." (PMID 36980845, 2023). "Of note, variants among the GRIN3A are considered to be more relevant to autism spectrum disorders or schizophrenia, while GRIN1, GRIN2A, GRIN2B, and GRIN2D are more epilepsy-related." (PMID 38075685, 2023). "As a result of this analysis, associations of four polymorphisms, GRIN2A rs9788936 (p = 0.001), GRIN2A rs8057394 (p = 0.011), GRIN2B rs7313149 (p = 0.016), and SLC1A2 rs12361171 (p = 0.040) with the intensity of symptoms in schizophrenia were identified." (PMID 36980845, 2023). "Parallel and multistep analysis in this research showed that SLC1A1, DRD2, DRD4, BDNF, ESR1, CDH2, GRIN2B, TNFa, GABBR1, and OLIG2 are common genes between schizophrenia and OCD which ESR1, DRD2, GABBR1, TNFa, and CDH2 are the most important individuals." (PMID 31086558, 2018). "In this sense, the DD/ID-associated SCHEMA mutants showed overall similar GSEA directional changes in the thalamus as the mutant of Grin2b, a gene associated with DD/ID/ASD but not schizophrenia." (PMID 41022686, 2025). "In the present study, we were able to detect the contribution of the GRIN2A, GRIN2B, GRM8, SLC1A2, and SLC17A7 genes of the glutamatergic system to determining the clinical heterogeneity of schizophrenia, which is important for the prognosis and outcome of the disease." (PMID 36980845, 2023). "In a cohort of 250 patients with chronic schizophrenia under clozapine treatment, the impact of SNPs in SLC1A1, Glutamate Ionotropic Receptor Kainate Type Subunit 2 (GRIK2), and N-methyl-D-aspartate receptor subunit 2B (GRIN2B) genes on OCS was assessed." (PMID 37627285, 2023). "A decrease in GRIN1 and GRIN2C mRNA were observed, but no changes in GRN2A and GRIN2B were detected in the PFC of schizophrenia subjects." (PMID 36833173, 2023). "Studies in rat models have shown that GRIN2A and GRIN2B expression is upregulated in the prefrontal cortex during childhood and adolescence, while a model of schizophrenia is characterized by an immature neurobiological phenotype with reduced GRIN2A and GRIN2B expression." (PMID 34685369, 2021). "SNV rs56069446 was found in the intron 8 of the GRIN2B gene, present in one healthy person in the control group and two people with non-remission schizophrenia." (PMID 33025395, 2021). "The GRIN2B and EXOC4 genes have been found to be in relation to schizophrenia." (PMID 30034349, 2018). "While the candidate genes used to construct this network were selected using evidence for disease implication derived from two different approaches, the network includes many additional genes of potential relevance to schizophrenia (e.g., GRIA2, GRIN1, GRIN2B, HOMER1, PICK1, and SNAP25)." (PMID 25484875, 2014).
schizophrenia (continued). "So far, independent replication approaches regarding BDNF, DLGAP3, and GRIN2B have not been conducted and further studies are needed to untangle the interplay of pharmacological and genetic risk factors for OCS in schizophrenia." (PMID 26556409, 2014). "Moreover, exome-sequencing studies revealed that rare damaging mutations in GRIN1, GRIN2A, and GRIN2B, which are expected to cause NMDAR hypofunction directly, are found in samples from schizophrenia patients, but not controls." (PMID 31824347, 2019). "Our conclusion is that selected single-nucleotide variants in GRIN1, GRIN2A, and GRIN2B genes of NMDA-R do not seem to be associated with both resistance to schizophrenia treatment with clozapine, and also with the occurrence of cognitive disturbances in schizophrenia." (PMID 33025395, 2021). "The study aimed to examine whether four selected single nucleotide variants in GRIN1, GRIN2A and GRIN2B encoding NMDA-R subunits, of which two have not been tested before, are linked with the selected clinical phenotype of cognitive dysfunction in schizophrenia." (PMID 33237434, 2021).
Cognitive impairment (88 papers, 2009 to 2026). Abnormal cognition is characterized by deficits in thinking, reasoning, or remembering. "Non-coding variants in GRIN2B have also been associated with short term and working memory, intelligence quotient and cognitive impairments in dyslexia and with other cognitive and behavioral traits." (PMID 40424442, 2025). "Previous studies have found that cognitive deficits in rats exposed to subchronic phencyclidine stimulation are associated with increased DNA methylation levels at the promoter region of the GRIN2B gene in the prefrontal cortex and hippocampus." (PMID 40438331, 2025). "Several studies have revealed the association between GRIN2B and clinically-manifested cognitive deficit symptoms, including memory performance." (PMID 26020650, 2015). "Several studies have explored the associated between GRIN2B and cognitive deficit symptoms, differential language lateralization, anti-psychotic-induced movement disorders, and clozapine-induced obsessive-compulsive symptoms." (PMID 26020650, 2015). "Our findings suggest that altered DNA methylation levels in the promoter region of the GRIN2B gene may be associated with reduced gene expression, which could potentially exacerbate cognitive impairment in these patients." (PMID 40438331, 2025). "This study found that, in addition to GRIN2B gene methylation levels, age-related factors were associated with cognitive impairment and were identified as significant risk factors for the increased severity of cognitive impairment in patients with bipolar depression." (PMID 40438331, 2025). "Furthermore, GRIN2B dysfunction has been implicated in motor and cognitive deficits in α-synuclein-induced mouse models, and treatment with a GRIN2B inhibitor has been shown to rescue motor impairments in PD." (PMID 39758784, 2024). "Genetic variations in the GluN2B coding gene (GRIN2B) have consistently been linked to West syndrome, intellectual impairment with focal epilepsy, developmental delay, macrocephaly, corticogenesis, brain plasticity, as well as infantile spasms and Lennox–Gastaut syndrome." (PMID 35893069, 2022). "Therefore, our study provided novel evidence for the association of GRIN2B with cognition deficit symptoms." (PMID 26020650, 2015). "A broad array of synaptic markers, including GRIN2A and GRIN2B, is often downregulated in prefrontal cortex in advanced age and in AD, with loss of components of the excitatory synapse, thereby potentially contributing to the modest cognitive deficits seen here in old animals." (PMID 35798912, 2022). "As an NDMA receptor subunit (NDMARs), Grin2b is essential for excitatory neurotransmission and has been proposed to contribute to cognitive impairment through the regulation of synaptic plasticity." (PMID 41150532, 2025). "In conclusion, patients with bipolar depression exhibit widespread cognitive impairment and abnormal DNA methylation levels in the GRIN2B gene." (PMID 40438331, 2025). "Studies have suggested that the GRIN2B gene plays a significant role in cognitive impairment." (PMID 40438331, 2025). "This work provides mechanistic insights into the molecular mechanisms underlying cerebellar synaptic dysfunction in ASD, indicating that Grin2b could represent a potential therapeutic target for cognitive impairment." (PMID 41150532, 2025). "DNA methylation levels in the GRIN2B gene promoter region may represent a potential therapeutic target for addressing cognitive impairment in bipolar depression." (PMID 40438331, 2025). "A variant of GRIN2B was found to be overexpressed in AD patients and individuals with mild cognitive impairment and may induce lower GRIN2B transcriptional activity as well as NR2B protein expression, which are associated with AD." (PMID 27983596, 2016). "Consequently, Grin2b represents a potential therapeutic target for addressing cognitive impairment." (PMID 41150532, 2025).
Cognitive impairment (continued). "Thus, Grin2b may represent a potential therapeutic target for addressing cognitive impairment in ASD." (PMID 41150532, 2025). "Correlation and regression analyses demonstrated that the severity of depression in patients with bipolar disorder did not significantly affect cognitive ability, the severity of cognitive impairment, or GRIN2B promoter methylation levels." (PMID 40438331, 2025). "This further implies that the relationship between GRIN2B promoter methylation levels and cognitive impairment is independent of depressive episodes." (PMID 40438331, 2025). "Our previous studies observed the genetic basis for SZ psychopathology symptoms, such as GRIN2B was related to cognition deficit symptoms, and CDNF2 was related to negative symptoms." (PMID 33173509, 2020).
epilepsy (81 papers, 2014 to 2026). A brain disorder characterized by episodes of abnormally increased neuronal discharge resulting in transient episodes of sensory or motor neurological dysfunction, or psychic dysfunction. "The predominant phenotypes associated with GRIN2B variants include developmental delay, intellectual disability, hypotonia, epilepsy, and language impairment." (PMID 41146259, 2025). "GRIN2B pathogenic variants cause multiple neurodevelopmental clinical phenotypes such as epilepsy, autism spectrum disorder (ASD), intellectual disability, sleep impairments, and movement abnormalities." (PMID 40827489, 2025). "De novo GRIN2B variants are one of the primary monogenic causes of epileptic encephalopathies, in which epilepsy is thought to worsen neurodevelopmental comorbidities." (PMID 40827489, 2025). "Pathogenic mutations in GRIN2B are an important cause of severe neurodevelopmental disorders resulting in epilepsy, autism, and intellectual disability." (PMID 40827489, 2025). "Mutations in the GRIN2B gene are associated with intellectual disability, developmental delay, motor impairments, autism spectrum disorder, and epilepsy in humans." (PMID 39519348, 2024). "About 70% of GRIN2A variants are likely to lead to the development of epilepsy, whereas 30% of individuals with GRIN2B variants have epilepsy." (PMID 36297409, 2022). "In various neuropsychiatric disorders, over 70% of the individuals with GRIN2A variants are diagnosed with epilepsy, whereas less than 30% of the individuals with GRIN2B variants have epilepsy." (PMID 35680847, 2022). "Some GRIN2B mutations (p.Val618Gly and p.Asn615Ile) were found in patients with early-onset epilepsy and epileptic encephalopathy." (PMID 35069111, 2021). "Such a glutamatergic hypofunction caused by an epigenetic control mechanism in Grin2b in the epilepsy model can also contribute to the pathophysiology of other neurodevelopmental disorders." (PMID 31992970, 2019). "From the epilepsy panel one novel variant was identified – GRIN2B c.3994G > T (p.Asp132Tyr)." (PMID 38756210, 2024). "Arpp21 and the autism gene Grin2b, that control dendritogenesis and branching were also Gatad2b dosage-sensitive genes differentially expressed in more than one cell cluster, with Grin2b being clinically associated with epilepsy and autism." (PMID 38238293, 2024). "For instance, some GRIN2B variants are linked to NDDs like ID, autism, and epilepsy." (PMID 39596430, 2024). "Animal models of epilepsy have implicated dysregulation of DNA methylation across different rat strains and show that status epilepticus modifies the methylation status of the glutamate receptor Grin2b." (PMID 37834093, 2023). "GRIN2B mutations are rare but often associated with patients having severe neurodevelopmental disorders with varying range of symptoms such as intellectual disability, developmental delay and epilepsy." (PMID 35741674, 2022). "Related studies have shown that GRIN1, GRIN2A, and GRIN2B mutations can lead to epilepsy." (PMID 35069111, 2021). "Alterations in GRIN2B may cause intellectual disability, epilepsy, autism, and sometimes microcephaly, movement disorder, cortical visual impairment, and occasionally cortical developmental malformation." (PMID 33806661, 2021). "An estimated 52% of patients with GRIN2B‐related neurodevelopmental disorder present with severe epilepsy, which is refractory to therapy in half of diagnosed cases." (PMID 40827489, 2025). "Overall, epilepsy in GRIN2B‐related neurodevelopmental disorders has been challenging to model, especially as complete loss of GluN2B‐NMDARs is perinatally lethal." (PMID 40827489, 2025). "The clinical phenotypes caused by GRIN2B LOF and GOF variants exhibit an overlap, including DD/ID, epilepsy, hypotonia, language impairment, movement disorders, and behavioral disturbances." (PMID 41146259, 2025).